FOXP3 (forkhead box P3)
Description:
Transcriptional regulator which is crucial for the development and inhibitory function of regulatory T-cells (Treg). Plays an essential role in maintaining homeostasis of the immune system by allowing the acquisition of full suppressive function and stability of the Treg lineage, and by directly modulating the expansion and function of conventional T-cells. Can act either as a transcriptional repressor or a transcriptional activator depending on its interactions with other transcription factors, histone acetylases and deacetylases. The suppressive activity of Treg involves the coordinate activation of many genes, including CTLA4 and TNFRSF18 by FOXP3 along with repression of genes encoding cytokines such as interleukin-2 (IL2) and interferon-gamma (IFNG). Inhibits cytokine production and T-cell effector function by repressing the activity of two key transcription factors, RELA and NFATC2. Mediates transcriptional repression of IL2 via its association with histone acetylase KAT5 and histone deacetylase HDAC7. Can activate the expression of TNFRSF18, IL2RA and CTLA4 and repress the expression of IL2 and IFNG via its association with transcription factor RUNX1. Inhibits the differentiation of IL17 producing helper T-cells (Th17) by antagonizing RORC function, leading to down-regulation of IL17 expression, favoring Treg development. Inhibits the transcriptional activator activity of RORA. Can repress the expression of IL2 and IFNG via its association with transcription factor IKZF4 (By similarity).
Synonyms: IPEX; JM2; XPID; AIID; PIDX; DIETER; SCURFIN
Tractability: PROTAC: UniProt records ubiquitination sites on it; ubiquitination databases record sites on it.
Safety:
Unwanted effects reported when the protein is acted on. In parentheses: how it was acted on, where the effect was seen, and who reports it.
acute renal toxicity (source: ClinPGx)
Gene: Protein-coding gene on chromosome X (49,250,436 to 49,264,800, reverse strand). Ensembl gene ENSG00000049768.
Subcellular location: Nucleus; Cytoplasm
Subcellular location (Human Protein Atlas): Nucleoplasm; Cytosol
Pathways (Reactome):
Gene expression (Transcription): RUNX1 and FOXP3 control the development of regulatory T lymphocytes (Tregs); RUNX1 regulates transcription of genes involved in WNT signaling
Gene Ontology:
Molecular function: DNA binding; DNA-binding transcription activator activity, RNA polymerase II-specific; DNA-binding transcription factor activity; histone acetyltransferase binding; histone deacetylase binding; NFAT protein binding; protein binding; protein homodimerization activity; sequence-specific DNA binding; sequence-specific double-stranded DNA binding; DNA-binding transcription factor activity, RNA polymerase II-specific; DNA-binding transcription repressor activity, RNA polymerase II-specific; NF-kappaB binding; RNA polymerase II cis-regulatory region sequence-specific DNA binding; transcription coregulator activity; identical protein binding; transcription corepressor activity
Biological process: negative regulation of cell population proliferation; negative regulation of cytokine production; negative regulation of DNA-templated transcription; negative regulation of immune response; negative regulation of interleukin-10 production; negative regulation of interleukin-17 production; negative regulation of interleukin-2 production; negative regulation of interleukin-4 production; negative regulation of T cell cytokine production; negative regulation of T cell proliferation; negative regulation of T-helper 17 cell differentiation; negative regulation of transcription by RNA polymerase II; negative regulation of type II interferon production; positive regulation of DNA-templated transcription; positive regulation of regulatory T cell differentiation; positive regulation of transcription by RNA polymerase II; regulation of transcription by RNA polymerase II; regulatory T cell differentiation; response to virus; T cell activation; CD4-positive, CD25-positive, alpha-beta regulatory T cell lineage commitment; chromatin remodeling; negative regulation of activated T cell proliferation; positive regulation of CD4-positive, CD25-positive, alpha-beta regulatory T cell differentiation; regulation of T cell anergy; and 7 more
Cellular component: cytoplasm; cytosol; nucleoplasm; nucleus; transcription regulator complex; chromatin; protein-containing complex
Gene-disease validity (ClinGen):
ClinGen rates the evidence that FOXP3 causes each of these diseases.
immune dysregulation-polyendocrinopathy-enteropathy-X-linked syndrome (X-linked): Definitive. Immunodysregulation - polyendocrinopathy - enteropathy - X-linked (IPEX) syndrome is a severe congenital systemic autoimmune disease characterized by refractory diarrhea, endocrinopathies, cutaneous involvement, and infections.
Homologues: Orthologues: macaque FOXP3 (99% identical), chimpanzee FOXP3 (91% identical), dog FOXP3 (91% identical), rabbit FOXP3 (90% identical), pig FOXP3 (90% identical), guinea pig FOXP3 (87% identical), mouse Foxp3 (86% identical), rat Foxp3 (86% identical), tropical clawed frog foxp3 (37% identical). Paralogues in human: FOXP1 (36% identical), FOXK2 (15% identical), FOXI3 (15% identical), FOXK1 (14% identical), FOXC1 (13% identical), FOXC2 (13% identical), FOXI2 (13% identical), FOXJ3 (13% identical), FOXJ1 (13% identical), FOXJ2 (13% identical), FOXE3 (12% identical), FOXL1 (12% identical), and 29 more.
Diseases named in the same sentence as FOXP3 in open-access papers:
FOXP3 is named in the same sentence as 845 diseases in open-access papers, as found by Europe PMC text mining. Sharing a sentence is not in itself a finding about the gene and the disease. The quoted sentences say what the papers report.
Autoimmunity (550 papers, 2007 to 2026). The occurrence of an immune reaction against the organism's own cells or tissues. "In contrast, female mice have random XCI, so only about half of their T cells express the maternal X. As a result, overall FoxP3 expression is lower, making them more susceptible to autoimmunity." (PMID 41546136, 2026). "Expression of the transcription factor FoxP3 is essential for Treg cell differentiation, maintenance, and suppressive function, and FoxP3 deficiency results in severe autoimmunity in mice and humans." (PMID 40726986, 2025). "The decades-long task of characterising this cell that can shut down autoimmunity finally intersected with the genetic mapping of the gene FOXP3, which underlies a rare autoimmune condition in humans and mice." (PMID 41255104, 2025). "Clinical studies have shown that mutations in FOXP3, a transcription factor essential for regulatory cell function, result in severe autoimmunity, including T1DM." (PMID 40370441, 2025). "It is possible that prolonged depletion of Foxp3 protein for multiple weeks or months will eventually cause more severe autoimmunity; however, this is likely to be reversible when Foxp3-transcribing cells are maintained." (PMID 40478934, 2025). "In T1DM, Bregs mitigate β-cell autoimmunity via IL-10 production and FOXP3-mediated pathways, but genetic mutations and dysfunctions in these mechanisms exacerbate autoimmunity." (PMID 40370441, 2025). "Defects in Foxp3+ T regulatory cells and Th2-skewing have been linked to both autoimmunity and the development of atopic disease, including IgE-mediated food allergy." (PMID 40065718, 2025). "This rare entity, displaying a set of different autoimmune disorders, is caused by mutation of the Foxp3 gene encoding the transcriptional factor that is necessary for Tregs to play their regulatory role." (PMID 41465370, 2025). "Genetic loss-of-function mutations in Foxp3 cause lethal multi-organ autoimmunity resulting from defects in TREG cell-suppressive activity, fitness, and lineage stability." (PMID 40478934, 2025). "Loss of Foxp3 function results in severe, often lethal autoimmunity, as seen in Scurfy mice and clinically in patients with IPEX (immune dysregulation, polyendocrinopathy, enteropathy, X-linked) syndrome." (PMID 39156895, 2024). "Loss of functional FOXP3 leads to serious autoimmune disorders in patients with immune dysregulation." (PMID 38584670, 2024). "Mutations that inactivate Foxp3 can result in severe autoimmune disorders, such as X-linked immune dysregulation polyendocrinopathy enteropathy syndrome (IPEX), multiple endocrine neoplasia, and enteropathy." (PMID 39290699, 2024). "Genetic mutations in Foxp3 generally occur along with functional Treg loss, resulting in different autoimmune disorders." (PMID 38584670, 2024). "It is known that mutations in the FOXP3 gene can lead primarily to autoimmune disorders, with the most well-known being IPEX syndrome." (PMID 38674427, 2024). "For example, mice that are double-deficient of Aire and Foxp3 develop severe autoimmunity early in life, and are more severely affected than both Aire and Foxp3 single-knockout mice." (PMID 38632993, 2024). "FOXP3-deficient mice and human males exhibit T cell-dependent inflammation and autoimmunity linked to exacerbated T cell activation and responses among other findings leading to premature death by day 25–35 in mice." (PMID 38438357, 2024). "Natural CD4+ Tregs are rendered unstable by loss of FoxP3 expression, which can ultimately lead to autoimmunity." (PMID 37771588, 2023). "The immunomodulatory effect of Foxp3+ Treg cells can be utilized in treating human autoimmune diseases, for some autoimmune disorders can lead to allergic reactions caused by hypersensitivity to antigens." (PMID 37795866, 2023).
Autoimmunity (continued). "In this issue of the JCI, Wang and authors report a Foxp3-regulated mechanism that facilitates strong Treg-DC interaction, which is associated with potent immunosuppression in murine models of autoimmunity, inflammation, and cancer." (PMID 38099491, 2023). "FoxP3 mutation has been reported as a rare X-linked recessive (IPEX) syndrome with aggressive autoimmunity with the clinical feature of immune dysregulation, polyendocrinopathy, and enteropathy in humans." (PMID 37771588, 2023). "Normal percentages of CD4+CD25+FOXP3+ T cells can be detected in the peripheral blood of IPEX 1 patients; however, these mutant FOXP3 Tregs are functionally impaired and are the main pathogenetic cause of the multi-organ autoimmunity in IPEX patients." (PMID 37189745, 2023). "Studies on Foxp3-deficient scurfy (SF) mice have shown that autoimmunity is accompanied by decreased gut bacterial diversity, which is restored by Foxp3+ Tregs administration." (PMID 37189745, 2023). "Despite the absence of tTreg cells, pTreg cells prevented early mortality and fatal autoimmunity commonly observed in Foxp3-deficient models of complete Treg cell deficiency, and largely maintained immune tolerance even as the ΔtTreg mice aged." (PMID 38164128, 2023). "In humans, the recognition of immune dysregulation, polyendocrinopathy, enteropathy, X-linked syndrome (IPEX) as an autoimmune disorder arising due to FOXP3 mutations, solidified FOXP3 as the key transcription factor in Tregs." (PMID 38077395, 2023). "Mutation in the Foxp3 gene, which is critical for the development of a suppressor population of T regulatory cells (Tregs), causes multi-organ autoimmunity and death of children in the first two years after birth." (PMID 36982782, 2023). "Lyon and colleagues demonstrated the importance of FOXP3 for Treg cell functions by their finding that mutation in the FoxP3 locus in mice leads to Treg dysfunction and severe autoimmunity." (PMID 36032080, 2022). "FOXP3 transcription factor is a crucial component associated with Tregs regulatory properties, and its loss was proved to cause autoimmune disorders – including IPEX syndrome as an example of sole Foxp3 mutation being the main cause." (PMID 36091019, 2022). "Loss or disruption of stable FOXP3 expression results in overt lymphoproliferative disease, autoimmunity, and graft rejection." (PMID 36341394, 2022). "Mice with FOXP3 deficiency develop the scurfy phenotype characterized by profound autoimmunity and inflammation multiple tissues." (PMID 35720275, 2022). "In this review we consider the function and regulation of FOXP3 both during homeostasis and autoimmunity, as well as how FOXP3 and mutations in key Treg genes influence Treg function and stability." (PMID 36032083, 2022). "Mutated FOXP3 is also associated with causing other severe autoimmune disorders, such as inflammatory bowel diseases and allergy accompanied by increased IgE levels." (PMID 36794233, 2022). "The significance of the FoxP3 transcription factor in immune tolerance was reported in IPEX in which mutation of FoxP3 resulted in the development of autoimmunity." (PMID 35669770, 2022). "The Treg cell population was gated on CD127low Foxp3+ cells as these expression profiles are associated with autoimmunity in MS." (PMID 36119053, 2022). "The mutated FOXP3 leads to the ‘scurfy’ phenotype in mice and the development of severe X-linked severe autoimmunity, immune-dysregulation poly-endocrinopathy enteropathy x-linked (IPEX) syndrome in humans." (PMID 36794233, 2022). "In humans and mice, the mutations in the FOXP3 locus on the X chromosome are associated with severe autoimmunity." (PMID 35563301, 2022). "The essential physiological function of Tregs for induction and maintenance of peripheral tolerance is demonstrated by the uncontrollable autoimmunity in mice and human that lack functional Tregs due to a mutation in forkhead box P3 (Foxp3) gene." (PMID 35704583, 2022).
Autoimmunity (continued). "Thirdly, we have found that patients with 18q deletions, irrespective of their autoimmune or allergic status, had CD4+CD25+FOXP3+ Treg cell deficiency—the key players controlling reactivity to self-antigens and preventing autoimmunity." (PMID 34867966, 2021). "Genetic polymorphisms in the FoxP3 gene and imbalances of regulatory T cells and autoimmunity have also been reported as-well-as polymorphisms of genes involved in Tregs activation and function." (PMID 33746959, 2021). "In this context, CNS2-deficient mice succumb to development of autoimmunity due to loss of Foxp3 and instability in Treg compartment." (PMID 34539668, 2021). "The crucial importance of FOXP3+ Treg can be demonstrated by severe syndromes caused by FOXP3 deficiency, which include multiple symptoms of autoimmunity and allergy, both in humans and in mice." (PMID 33572097, 2021). "The key obstacle to clinical application of human inducible regulatory T cells (iTreg) as an adoptive cell therapy in autoimmune disorders is loss of FOXP3 expression in an inflammatory milieu." (PMID 34021231, 2021). "There is a counterbalance between pathogenic (Th17) T cells that induce autoimmunity and regulatory (Foxp3+) T-cells that inhibit autoimmune tissue injury." (PMID 34868786, 2021). "Loss of Foxp3 results in autoimmunity in the normal situation, while deficiency of Foxp3 unleashes immunosuppressive capacities and, hence, improves tumoricidal activities." (PMID 33968014, 2021). "Mice with mutations or deletions of FOXP3 develop lethal autoimmunity and humans with mutations in FOXP3 develop a rare disease called immunodysregulation polyendocrinopathy enteropathy X-linked (IPEX) syndrome." (PMID 33564037, 2021). "Although the -924 G > A FOXP3 variant (rs2232365) was evaluated in other autoimmunity diseases this is the first study to evaluate this variant in SLE patients." (PMID 33686190, 2021). "The identification of early signs of multiple autoimmunity in males should prompt clinicians to deeper investigations aimed at identifying other signs of immune dysregulation, possibly sustained by FOXP3-mutated Tregs." (PMID 33692972, 2021). "Of note, deficiencies in Foxp3 cause lymphoproliferation and multiorgan autoimmunity in Scurfy mutant mice and humans with immunodysregulation polyendocrinopathy enteropathy X-linked." (PMID 34040168, 2021). "The pathological importance of Foxp3 instability in the generation of pathogenic Th17 cells in autoimmunity has been well established." (PMID 34858422, 2021). "In humans, many mutations and/or alternatively spliced variants of the FOXP3 gene are strongly associated with an extremely rare and severe autoimmune disorder termed immunodysregulation, poly-endocrinopathy and enteropathy, X-linked syndrome (IPEX)." (PMID 34768829, 2021). "This recognition requires both the zinc finger/leucine zipper region and Fkh protein domains, as mutations in either abrogate FOXP3 function and result in autoimmunity." (PMID 33532929, 2021). "For proper development and function of Treg cells, Tregs are crucially depend on the forkhead box transcription factor FOXP3; loss of Foxp3 function in humans and rodents results in devastating autoimmunity." (PMID 34881246, 2021). "Humans bearing mutations in the forkhead box P3 (FOXP3) gene, which leads to lethal autoimmunity, helped identify FOXP3 as the signature transcription factor for Treg lineages." (PMID 33868263, 2021). "Several studies have demonstrated that the migration of Th17 cells into the CNS is the key pathogenic process in EAE mice and that Foxp3 deficiency is closely associated with spontaneous autoimmunity development." (PMID 32983109, 2020). "Mutation of Foxp3 in mice leads to severe autoimmunity disease and multi‐organ infiltration owing to Tregs deficiency." (PMID 32729205, 2020). "a rare disease associated with FOXP3 dysfunction, leading to Treg impairment and severe autoimmunity." (PMID 32793236, 2020).